KCNJ2 (potassium inwardly rectifying channel subfamily J member 2)
Diseases named in the same sentence as KCNJ2 in open-access papers (continued):
Sharing a sentence is not in itself a finding about the gene and the disease.
tumor (14 papers, 2014 to 2026). "KCNJ2's associations with critical signaling pathways, including those involved in tumor progression and immune regulation, suggest it may play an important role in ccRCC biology." (PMID 40314029, 2025). "These examples highlight the urgent need to investigate KCNJ2's function in ccRCC to gain a better understanding of its potential influence on tumor progression and therapeutic strategies." (PMID 40314029, 2025). "Our findings reveal the functional role of KCNJ2 in promoting tumor progression and metabolic reprogramming in ccRCC, highlighting its therapeutic potential as a novel target for ccRCC treatment." (PMID 40314029, 2025). "These interactions merit further exploration to delineate the precise mechanisms by which KCNJ2 influences immune evasion and tumor progression." (PMID 40314029, 2025). "The observed correlation between KCNJ2 expression and immune checkpoint markers suggests a possible role in modulating the tumor immune microenvironment." (PMID 40314029, 2025). "Specifically, potassium channels such as Kv10.2 (EAG2), Kv2.2 (KCNB2), Kv1.5 (KCNA5), and Kir2.1 (KCNJ2) were upregulated in the MB tumor tissues and primary cultures." (PMID 40150732, 2025). "This functional importance highlights the need for further experimental studies to investigate KCNJ2's role in tumor cell behavior and the TME." (PMID 40314029, 2025). "The injection of KCNJ2/Kir2.1-overexpressing H69 and H446 cells resulted in significantly increased tumor weights compared with the injection of the corresponding NC cells." (PMID 25880778, 2015). "Additionally, functional studies examining KCNJ2 at both the mRNA and protein levels in ccRCC tissue samples are crucial for confirming its role in tumor progression and prognosis." (PMID 40314029, 2025). "However, significant differences in KCNJ2 mRNA levels were observed when comparing the primary tumor size and extent, specifically between T1 and T4 stages, T2 and T4 stages, and T3 and T4 stages (all p < 0.05)." (PMID 40314029, 2025). "Therefore, we considered, combining with a biological delivery system that targets hypoxic areas of the tumor, the KCNJ2 inhibitors would exhibit more effective for anti-OS and evade nonspecific toxicity to other tissues." (PMID 36864422, 2023). "Additionally, the injection of KCNJ2/Kir2.1-overexpressing H69 and H446 cells resulted in earlier tumor formation compared with the injection of NC cells." (PMID 25880778, 2015). "Moreover, consistent with the results obtained in vitro, KCNJ2/Kir2.1 promoted tumor growth in a xenograft nude mouse model." (PMID 25880778, 2015). "The results showed that the expression of IPCEF1, TFF3, GLT8D2, TPO and DIO1 were downregulated in the tumor group and DPP4, LRP4, CDH3, KCNJ2, CLDN1, GABRB2, FN1 were upregulated in the tumor group." (PMID 39513122, 2024). "In tumor 748d3ff3-8699-4519-8e0f-26b6a0581bff, another neo-TAD was predicted to form as a result of the deletion that merged the TADs of TOB1-AS1 and the downstream portion of KCNJ2." (PMID 39051548, 2024). "However, with KCNJ2/Kir2.1-knockdown H69AR and H446AR cells, the average tumor weight decreased to 12-25% of that of the tumors originating from the cells transfected with shNC." (PMID 25880778, 2015). "For instance, in medulloblastoma, KCNJ2 shows elevated expression specially in non-WNT/SHH subgroups, where it plays a key role in driving tumor cell invasion and metastasis, and this process is facilitated activation of the Notch2 signaling pathway." (PMID 40314029, 2025).
cancer (11 papers, 2013 to 2025). A tumor composed of atypical neoplastic, often pleomorphic cells that invade other tissues. "In cancer, KCNJ2 has been implicated in various malignancies, exhibiting oncogenic effects by influencing cell proliferation and survival." (PMID 40314029, 2025). "Because potassium channels contribute to angiogenesis in cancer, it is worth investigating a possible association between cerebrovascular development and KCNJ2 variant." (PMID 35174115, 2021). "Additionally, the association of KCNJ2 with glucose metabolism and immune regulation within the context of ccRCC underscores its intricate role in cancer biology." (PMID 40314029, 2025). "KCNJ2, encodes the Kir2.1 protein, a key member of the inwardly rectifying potassium channel family, essential for potassium ion regulation and cellular excitability in diverse tissues such as neurons, skeletal muscle, cardiac myocytes, immune, and carcinoma cells." (PMID 40314029, 2025). "The protein encoded by the KCNJ2 gene is a complete membrane protein and inward rectifier potassium channel that conducts strong inward rectifier K current in various tissues and cell types, including neurons, skeletal muscle, cardiomyocytes, immune system, and cancer cells." (PMID 37228444, 2023). "Recent studies have highlighted the role of KCNJ2 in various cancers beyond the primary focus of this study." (PMID 40314029, 2025). "Our findings not only align with existing research on the role of KCNJ2 in cancer but also offer new insights into its specific functions in ccRCC." (PMID 40314029, 2025). "In neurons, skeletal muscle, cardiac myocytes, immune system cells, and carcinoma cells, KCNJ2 conducts an inward rectifying potassium current." (PMID 36864422, 2023). "This specificity highlights the multifaceted functions of KCNJ2 and underscores the necessity for targeted investigations to clarify how different ion channels may exert varied effects across distinct cancer types." (PMID 40314029, 2025). "KCNJ2, part of the classical inward rectifying potassium channel subfamily, facilitates inward rectifying potassium currents in diverse cell types such as neurons, skeletal muscle cells, cardiac myocytes, immune cells, and cancer cells." (PMID 40314029, 2025). "Prior research has demonstrated that KCNJ2 is capable of advancing the progression of multiple cancer types, regardless of the underlying molecular mechanisms associated with its inward rectifying potassium current." (PMID 40314029, 2025). "Furthermore, our results indicate that KCNJ2 may influence key pathways related to proliferation, migration, invasion, apoptosis, and glucose metabolism in ccRCC cells, thereby contributing to the aggressive phenotype of this cancer." (PMID 40314029, 2025). "Knockdown of KCNJ2/Kir2.1 expression using KCNJ2/Kir2.1 shRNA in H69AR and H446AR cells inhibited cell growth and sensitized the cancer cells to chemotherapeutic drugs by increasing cell apoptosis and cell cycle arrest." (PMID 25880778, 2015). "Previous studies have indicated that KCNJ2 can promote the progression of a series of cancers, independent of the molecular mechanism of the inward rectifying potassium current." (PMID 36864422, 2023). "Moreover, we implicate several of these gene hits not only in ccRCC for the first time (BHLHB3, CAMK1, CDH13, ENPP3, KCNJ2, KSR1, PLOD2, and TCF8), but also in a cancer model for the first time (CEP290, EFCAB3, PGBD5, RAPGEF5, SSPN, and TOX2)." (PMID 24979721, 2014). "Membrane localization of KCNJ2/Kir2.1 and MRP1/ABCC1 was observed in cancer cells, whereas no positive MRP1/ABCC1 staining was observed in normal lung alveolar epithelium." (PMID 25880778, 2015).
cardiovascular disease (10 papers, 2015 to 2025). "In this article, we report a novel mutation (p.Phe58Ser) within the KCNJ2 gene in an Italian proband of a family where both ASDs and cardiovascular disease segregate." (PMID 29615871, 2018).
cardiac disease (5 papers, 2017 to 2026). "Abnormality of Kir2.1 channels arising from KCNJ2 mutations has been identified in various cardiac diseases." (PMID 29290967, 2017). "In a study performed on 31 SIDS cases, 20% of the cases presented variants of uncertain significance related to cardiac disease–associated genes and in 6% the variants were considered potentially informative (SCN5A Arg1316Gln and KCNJ2 Glu16Gly)." (PMID 41062843, 2026). "GJA1 and KCNJ2, both targeted by miR-1, are two ion channel genes, which are known to play a major role in cardiac disease and development." (PMID 31836860, 2019).
KCNJ2 also shares sentences with these, for which no sentence is quoted: cardiac arrhythmias (21 papers); Obesity (10); infection (9); short QT syndrome type 3 (8); autism (5); genetic disorders (5); heart failure (5); endothelial dysfunction (4); atrioventricular block (3); Brugada syndrome (3); dilated cardiomyopathy (3); Hypercholesterolemia (3); hypokalemic periodic paralysis (3); Insulin resistance (3); ischemia (3); Alzheimer disease (2); Anxiety (2); astrocytoma (2); atherosclerosis (2); cerebral small vessel disease (2); dyslipidemia (2); Hypokalemia (2); Intellectual disability (2); ischemic stroke (2); medulloblastoma (2); neurological disorders (2); polymorphic ventricular tachycardia (2); sick sinus syndrome (2); Stroke (2); thyrotoxicosis (2).
A further 62 diseases each share a sentence with KCNJ2 in 1 paper.